ATM (ATM serine/threonine kinase)
Diseases named in the same sentence as ATM in open-access papers (continued):
Sharing a sentence is not in itself a finding about the gene and the disease.
melanoma (continued). "There also seemed to be a marginal, but not statistically significant, increase in the percentage of negative and strong p-ATM expressions from dysplastic nevi to primary melanoma (p = 0.592)." (PMID 26275218, 2015). "While ATM inhibition was not sufficient to sensitize melanoma cells to ionizing radiation, cells lacking ATM activity were found to be sensitive to temozolamide treatment." (PMID 26275218, 2015). "Moreover, the rest of SASP-related genes recruited in our risk-scoring model including HLA-B, TPMT, ATM, CD59, TRIM21, and ASPRV1 have not been well studied in melanoma, indicating their potential of novel therapeutic target." (PMID 40864319, 2025). "To determine whether melanomas that have dysregulation of the MRN complex or ATM may be sensitive to PARP inhibitors, we performed independent knockouts of ATM, NBN, and MRE11 in 2 melanoma cell lines, MeWo (TWT) and A375 (BRAF-mutant), followed by olaparib cell viability assays." (PMID 38758740, 2024). "Our study shows that PARP inhibitor treatment is a valuable therapy option for patients with melanoma, either as a single treatment or as a combination with MAPK inhibitors depending on ATM expression, which could serve as a novel biomarker for treatment response." (PMID 37674529, 2023). "Interestingly, ATM PV/LPVs frequency was second to CDKN2A only in patients with a family history of PC (5.4%) and was found at a frequency of 3.3% in patients with familiarity for melanoma." (PMID 36139606, 2022). "Specifically, we will focus on PARP, ATM, CHK1, WEE1 and ATR inhibitors, for which preclinical data as single agents, taking advantage of synthetic lethal interactions, and in combination with chemo-targeted-immunotherapy, have been growing in melanoma, encouraging the ongoing clinical trials." (PMID 35563772, 2022). "The combined application of tRA and ATM inhibitor dramatically inhibited melanoma growth whether the xenografts were UV-irradiated or not, which was not due to the toxicity of the reagents as the body weights of all the mice were not that different." (PMID 31766690, 2019). "The study also did not analyze p-ATM expression in melanoma patients." (PMID 26275218, 2015). "A highly significant overlap of transcript expression in melanoma cell lines after cisplatin treatment with transcripts involved in DNA repair and DNA damage response genes BRCA1, BRCA2, ATM and CHEK2 was observed, which may be compensating for diminished NER capacity." (PMID 23940574, 2013). "Besides its nuclear role in double-strand breaks and cell cycle checkpoint, cytoplasmic ATM plays noncanonical roles in the regulation of organelle/oxidative/energetic metabolism, which may involve melanoma biogenesis, and potentially, melanoma treatment." (PMID 34262154, 2021). "Similarly, patients with negative expression of p-ATM might have had larger tumors, faster melanoma progression and consequently worse prognosis." (PMID 26275218, 2015). "Currently, there are at least three ATM inhibitors (AZD0156, KU-60019, AZD1390) undergoing clinical trials in solid tumors, but so far, none of these were investigated in melanoma, neither as a single agent nor in a combination regimen." (PMID 35563772, 2022). "Percentage of patients with negative p-ATM expression appeared to increase from stage I to stage III and then decreased from stage III to stage IV, though the differences between melanoma stages were not statistically significant." (PMID 26275218, 2015). "We initially treated the three SPR-proficient melanoma strains in our collection with (i) 10 mM caffeine known to inhibit both ATR and ATM, or (ii) 30 μM wortmannin which inhibits ATM and DNA-PK but not ATR followed by exposure to IR or UV." (PMID 24416382, 2014).
colorectal cancer (117 papers, 2011 to 2026). A primary or metastatic malignant neoplasm that affects the colon or rectum. "Chemosensitivity and radiosensitivity are associated with the prognosis of colorectal cancer, and the expression of the ataxia-telangiectasia mutated (ATM) protein plays an essential role in these processes." (PMID 40144209, 2025). "The present study examined the relationship between ATM expression and the survival outcomes of colorectal cancer patients and explored the underlying mechanism and promising therapeutic strategies." (PMID 40144209, 2025). "For example, OLA is proving to be effective in the treatment of cancers with ATM mutations, such as colorectal cancer, for which REG is used." (PMID 39771554, 2024). "Only one case report study reported that two microsatellite stable colorectal cancer (MSS CRC) patients with ATM mutations benefited from anti-PD-1 checkpoint inhibitors." (PMID 39033176, 2024). "In the present study, the combination of ataxia telangiectasia-mutated serine/threonine kinase (ATM) and checkpoint kinase 1 (Chk1) inhibition exhibited synergistic antitumor effects and induced synergistic lethality in colorectal cancer cells at a low dose." (PMID 36765693, 2023). "In this analysis, the top three most common genes with founder mutations were PRKDC (n = 31 colorectal cancer samples from the TCGA dataset), ATM (n = 18 samples), and BRCA2 (n = 17 samples)." (PMID 35054819, 2022). "In total, 20 of the 24 ATM mutations (83.3%) in BRAF mutated colorectal cancers are categorized as likely oncogenic." (PMID 36079062, 2022). "Given the reported ability of ATM loss to sensitise to ATR/CHK1 inhibition, and our recent finding that ATM loss synergises with IGF axis inhibition, we also tested ATM-deficient SK-CO-1 colorectal cancer (CRC) cells." (PMID 34773074, 2022). "This suggests that ATM mutations in BRAF mutated colorectal cancers are associated with a better prognosis sub-group such as MSI high." (PMID 36079062, 2022). "Somatic mutations of the ATM gene, as a DNA repair gene, occur in many tumor types including colorectal cancer." (PMID 35723313, 2022). "A high prevalence of ATM mutations is observed in BRAF mutated colorectal cancers in both TCGA and DFCI cohorts." (PMID 36079062, 2022). "ATM is frequently mutated in colorectal cancer and, in a group of 227 Italian patients, it was observed unexpectedly that the 15% ATM mutated patients showed a significantly longer median overall survival compared with ATM wild-type tumors." (PMID 34771661, 2021). "Mutations in ATM have been reported in various solid tumors, including endometrial cancer, bladder cancer, and colorectal cancer." (PMID 34638295, 2021). "According to The Cancer Genome Atlas (TCGA) pan cancer studies, ATM somatic mutations are most frequently found in endometrial cancer (~18.7%), followed by bladder cancer (~12.9%) and colorectal cancer (~11.8%)." (PMID 33224881, 2020). "ATM gene, encoding a protein involved in DNA damage response, is frequently mutated in colorectal cancer (CRC), but its potential role as predictive and prognostic biomarker has not been fully investigated." (PMID 30814645, 2019). "In a set of 137 NSCLC and 154 colorectal cancer specimens we identified tumoral loss of ATM protein expression in 9.5% and 3.9% of cases, respectively, demonstrating the potential utility of this method." (PMID 27602502, 2016). "Anti-ATM antibody ab32420 identified ATM reduction or loss in 158 of 314 (59%) of colorectal cancers and this was associated with worse disease-free survival." (PMID 27259260, 2016). "In conclusion, we have demonstrated an association between presence of Ku70 and CIN in colorectal cancer and confirmed an association between ATM expression and superior DFS." (PMID 23154512, 2012).
colorectal cancer (continued). "A similar phenomenon has been seem in patients undergoing chemotherapy with loss of ATM expression within their tumours, showing a tendency towards worse survival in colorectal cancer." (PMID 23154512, 2012). "This study demonstrated that BMN673 could significantly inhibit growth of ATM-deficient colorectal cancer cells through synthetic lethal." (PMID 41266732, 2025). "To explore whether radiation could amplify the effect of ATM on MHC class I expression, we detected the expression level of MHC class I in the membrane of ATM-deficient and ATM-proficient colorectal cancer cells after radiation and IFN-γ stimulation." (PMID 39033176, 2024). "Importantly, loss of ATM has been shown to increase PARPi sensitivity in lung, prostate, and colorectal cancers." (PMID 38807759, 2024). "In this cohort, 11 variants in ATM were identified, most of them diagnosed with colorectal cancer." (PMID 36232851, 2022). "In colorectal cancer, the loss of ATM protein expression is associated with worse prognosis." (PMID 35723313, 2022). "ATM participates in the maintenance of genomic stability and DNA damage repair and has been implicated as a tumor suppressor in various cancer types including lung adenocarcinoma, B-cell lymphoma, and colorectal cancer." (PMID 35281811, 2022). "In general, the cancers with higher ATM or ATR mutation frequencies tend to have higher number of mutated residues; for example, endometrial cancer, non-Hodgkin’s lymphoma, and colorectal cancer, with an ATM mutation frequency of 8–10%, each has over 100 mutated residues." (PMID 33742106, 2021). "Second, it is possible that we missed pathogenic germline variants in moderate penetrance colorectal cancer genes such as ATM, SMAD3, or high penetrance syndromes primarily associated with other cancers such as BRCA1 and BRCA2, which were not part of our panel." (PMID 31647837, 2019). "Our results provide the evidence that rs189037 in ATM may increase the susceptibility of colorectal cancer in a Chinese population." (PMID 29928473, 2018). "Intraperitoneal injection with CS-6 inhibited tumor growth in nude mice with colorectal cancer, and promoted the protein expression of phosphorylated H2A histone family member X (γH2AX), p62, phosphorylated Ataxia-telangiectasia mutated kinase (p-ATM) and LC3 I/II." (PMID 40417224, 2025). "Additionally, we found that ataxia-telangiectasia mutated (ATM) kinase inhibitor AZ32 could sensitize ABCG2-overexpressing colorectal cancer cells to ABCG2 substrate chemotherapeutic drugs mitoxantrone and doxorubicin by retaining them inside cells." (PMID 34094985, 2021). "Loss of ATM expression might serve as a biomarker of poor prognosis in colorectal cancer." (PMID 23154512, 2012). "Colorectal cancer (CRC) is a serious threat to human health, with an approximate 14% mutation rate in the ataxia telangiectasia-mutated (ATM) gene, which is involved in homologous recombination repair." (PMID 41266732, 2025). "While the ATM mutational status of these patients was not disclosed, this observation aligns with preclinical studies indicating that the loss or downregulation of ATM is synthetic lethal with PARP inhibitors in gastric and colorectal cancer cell lines." (PMID 38807759, 2024). "For example, DNA damage response mechanisms involving the cell cycle kinases ataxia telangiectasia mutated (ATM) and checkpoint kinase 2 (CHK2) are known to contribute to the development of colorectal cancer." (PMID 37631237, 2023). "We were able to demonstrate murine ATM inhibition by 1 in CT26 murine colorectal cancer cells (and reduction of downstream target pKAP1) using western blot, indicating binding of 1 to murine ATM." (PMID 35962885, 2022).
colorectal cancer (continued). "The patient with an MLH1 p.Ser577 = variation had a history of colorectal cancer, and the patient with an ATM p.Phe2558fs variation had a history of gastric cancer." (PMID 35171259, 2022). "To confirm these findings, we generated an additional ATM KO in the colorectal carcinoma cell line DLD1, for which a BRCA2 KO was already available." (PMID 36969741, 2022). "Enrichment of samples with 15 or more short duplications is positively associated with colorectal cancer (q = 1.2 × 10−9) and driver mutations in PARK2 (q = 0.0003) and ATM (q = 0.008)." (PMID 34253237, 2021). "ATM can also protect colorectal cancer cells and lymphoblastoid cells from hydroxyurea-induced cell death, but seems less effective than ATR." (PMID 34685500, 2021). "Previous studies showed that Escin, a triterpene saponin from horse chestnut seeds, induced apoptosis in human colorectal cancer cells via p62/ATM/γH2A.X-mediated DNA damage." (PMID 33802884, 2021). "Similar results were observed in gastric cancer cell lines, and in colorectal cancer cell lines with shRNA depletion of ATM." (PMID 32183301, 2020). "ATM and BRCA1 were unexpectedly associated with moderately increased risk for colorectal cancer in this study, with 20.7% and 19.4% of PV carriers in these genes meeting testing criteria for Lynch syndrome." (PMID 31406321, 2020). "Low ATM was also associated with advanced TNM stage and poor 5-year OS in patients with colorectal cancer (CRC)." (PMID 33224881, 2020). "ATM and PIK3CA mutations were present in a quarter of the patients, again a frequency expected for colorectal cancer." (PMID 32784964, 2020). "BMAL1 overexpression increases the sensitivity of colorectal cancer cells to oxaliplatin by ATM pathway activation." (PMID 31014368, 2019). "Similar results were obtained by using xenograft mouse models showing that statin sensitized gastric and colorectal cancer cells to radiotherapy through modulation of the ATM/AMPK/p21 pathway." (PMID 29950990, 2018). "And this result consisted with published studies that ATM had a role in the early stage of colorectal cancer development." (PMID 29928473, 2018). "In addition, rs189037 belongs to the eQTL of ACAT1 and ATM, which have been reported to be associated with carcinogenesis of colorectal cancer, so we speculate this genetic variant may increase the colorectal cancer susceptibility by influencing their expression." (PMID 29928473, 2018). "Moreover, we found that increased colorectal cancer risk correlated with rs189037 was more significant in subgroup of elder individuals which suggested that promoting effects of ATM variants on colorectal cancer may be modulated by specific epidemiological features." (PMID 29928473, 2018). "Similar inhibition of pRAD50 (68%) was observed following ATM inhibitor treatment post irinotecan in a colorectal cancer xenograft model." (PMID 30385821, 2018). "We wished to ascertain the relationship of altered expression of the DSB repair proteins γ-H2AX (gamma-H2AX), ATM and Ku70 with biological and clinico-pathological features of colorectal cancer." (PMID 23154512, 2012). "We have carried out a large-scale investigation of the expression of the double strand break repair proteins γ-H2AX, ATM and Ku70 in colorectal cancer." (PMID 23154512, 2012). "Low ATM expression level may be a marker of poor survival in colorectal cancer and contributes to resistance to therapy." (PMID 40144209, 2025).
colorectal cancer (continued). "ATM inhibitors have been explored in preclinical and clinical studies, but remain widely unknown in colorectal cancer due to the limited number of clinical cases." (PMID 39033176, 2024). "Whether targeting ATM can be used as an opportunity for immunotherapy of colorectal cancer remains unknown." (PMID 39033176, 2024). "Indeed, 21 of 24 BRAF and ATM mutated colorectal cancers (87.5%) in TCGA are MSI or POLE subtype while among BRAF mutated, in ATM wild type cancers only 55.3% belong to these subtypes (Fisher’s exact test p = 0.01)." (PMID 36079062, 2022). "In addition to ATM, other genes related to DNA damage response (DDR) are mutated in smaller percentages of colorectal cancers and show a predilection for BRAF mutated cancers." (PMID 36079062, 2022). "Different NGS studies have reported that up to 18% of patients under 50 years old, diagnosed with colorectal cancer, have a PV in genes that are not traditionally associated with this neoplasm such as ATM, CHEK2, and BRCA1/2." (PMID 36232851, 2022). "A 55-year-old patient with KRAS and BRAF wild-type advanced colorectal cancer had 100% ATM IHC loss in his tumor, but NGS did not detect an ATM mutation." (PMID 32568634, 2020). "Since MRN is closely related to the regulation of ATM and γ-H2AX, it too could be considered as a biomarker for colorectal cancer, especially in certain subtypes such as MMR-deficient CRCs." (PMID 30769804, 2019). "Indeed, treatment of colorectal cancer cells with NW457 resulted in rapid degradation of ATM and CHK1, two essential upstream kinases of the DNA damage response." (PMID 27259245, 2016). "By comparison, ATM expression might be used in the near future as a biomarker of prognosis in colorectal cancer." (PMID 23154512, 2012). "By targeting the weaknesses of ATM-deficient cancer cells, this approach not only boosts the effectiveness of ATR inhibitors but also introduces a promising strategy to overcome chemoresistance, paving the way for more innovative and effective treatments for colorectal cancer." (PMID 40256842, 2025). "Besides, aberrant methylation of ATM was also detected in colorectal cancers and adenomas." (PMID 28794688, 2017). "Genetic depletion of TTI1 destabilizes ATM and ATR, attenuates DNA damage signaling, impairs double-strand break repair, and sensitizes colorectal cancer cells to 5-fluorouracil and oxaliplatin." (PMID 42283915, 2026). "The other cancers seen in the pedigrees of the 2 patients with an ATM gene VUS at c.7502 A > G were leukemia in a third-degree relative and colorectal cancer in second- and third-degree relatives." (PMID 37277882, 2023). "In the present study, we examined the efficacy of the combined treatment of the ATM inhibitor (ATMi) KU-60019 and Chk1i LY2606368 against cultured colorectal cancer cells and tumors in syngeneic tumor model mice." (PMID 36765693, 2023). "For breast and colorectal cancers (n = 731), PVs were most frequent in CHEK2 excluding I157T (2.2%, 95% CI 1.4–3.5%), ATM (1.2%, 95% CI 0.6–2.4%), MLH1 (0.8%, 95% CI 0.3–1.9%), and PMS2 (0.7%, 95% CI 0.3–1.7%)." (PMID 36856935, 2023).